IL6 (interleukin 6)
Diseases named in the same sentence as IL6 in open-access papers (continued):
Sharing a sentence is not in itself a finding about the gene and the disease.
glioma (continued). "Furthermore, SP also induces phosphorylation of p38 MAPK which mediates SP-induced IL-6 expression in U-373 MG glioma cells by a mechanism independent of ERK1/2 (p42/44 MAPK), PKC, and NF-κB activation." (PMID 39941886, 2025). "Furthermore, IL-6 gene amplification was absent in low-grade and anaplastic tumors (0/17) but present in 15 out of 36 glioma specimens (42%)." (PMID 40143164, 2025). "TAMs produce many proteins that can enhance glioma proliferation and/or migration, such as stress-inducible protein 1 (STI1), epidermal growth factor (EGF), colony-stimulating factor 1 (CSF-1), chemokine ligand 2 (CCL2), interleukin-6 (IL-6), and transforming growth factors: TGF-β and -β2." (PMID 39452154, 2024). "Also, in another study, it was discovered that nano-DOX impedes STAT3 activation in tumor cells and lowers IL-6 production in astrocytes, indicating that nano-DOX has the potential to break the STAT3/IL-6-mediated reciprocal activation loop among glioma cells and astrocytes." (PMID 38686045, 2024). "In addition to these, MAPKAPK2 is positively correlated with IL6, IL6R, IL10, IL10RB, TGFβ1, etc., in the present study, which may facilitate the glioma progression." (PMID 38322416, 2024). "In addition, IL-6 promoted tumor angiogenesis and tumor growth by activating STAT3 in glioma." (PMID 38259287, 2023). "In glioblastoma, for instance, IL-6 has been reported to induce NFκB, resulting in STAT3 activation and greater tumor aggressiveness, while inhibition of IL-6/STAT3 and NFκB decreases glioma growth, and these results support an impact of inflammation on brain tumor development." (PMID 36232813, 2022). "In glioma tissues, syndecan-binding protein (SDCBP), which controls the proliferation and invasion of cancer cells, is positively correlated with IL-6 expression level, and IL-6 stimulation induces SDCBP expression at mRNA and protein levels in a dose- and time-dependent manner." (PMID 36591515, 2022). "Additionally, the evaluated glioma cell lines showed increases in total Pyk2 and FAK protein expression upon treatment with SDF-1α, IL-6, and EGF, indicating regulation of Pyk2 and FAK signaling at the level of protein synthesis, in addition to the regulation of phosphorylation." (PMID 34944779, 2021). "IL-6 secreted by M2 macrophages promoted glycolysis of GBM cells by phosphorylating PGK1 via 3-phosphoinositide-dependent protein kinase 1 (PDPK1), and quinolinic acid secreted by microglia was taken up by glioma cells for the synthesis of NAD+ to resist oxidative stress." (PMID 34211978, 2021). "In addition, we reported that hypoxia treatment induced a significant increase in IL-6 secretion in the glioma cell culture supernatants, but we did not investigate the effects of secreted IL-6 on the immunosuppressive tumor microenvironment." (PMID 33828078, 2021). "The results indicated that DEGs are enriched in immune-related biological processes, including IL2/STAT5, IL6/JAK/STAT3, and Interferon-γ response signaling and the two categories identified by consensus clustering are correlated with immune infiltration of glioma." (PMID 33123464, 2020). "Previous studies show gliomas contain a plenty of macrophages, and tumor-associated macrophages correlate with progression and angiogenesis of gliomas by several ways, including: microRNA-macrophage feedback loop, extracellular lipid loading and cytokines like OPN, IRGM, IL-6." (PMID 32509446, 2020). "Similarly, in glioma, CD163+ TAMs induce the VM by enhancing the secretion of IL-6 via PKC pathway." (PMID 32092078, 2020). "Lastly, we have elaborated that TNF-α/IL-6/sIL-6R could downregulate the proliferation rate and the tumorigenicity of glioma cells, but not eliminate them." (PMID 33227992, 2020).
glioma (continued). "Previous studies have demonstrated that IL‐6 recruits gp130 by binding to its receptor, the membrane‐bound IL‐6 receptor (mIL‐6R), to activate STAT3.36, 37, 38 Moreover, CD9 stabilizes gp130 to activate STAT3 in glioma stem cells by preventing its ubiquitin‐dependent lysosomal degradation." (PMID 31837208, 2020). "Moreover, it suggests that circulating IL‐6 and CRP may serve as powerful biomarkers for a poor prognosis in glioma patients." (PMID 31599129, 2019). "Moreover, our meta‐analysis suggests that circulating IL‐6 and CRP may serve as powerful biomarkers for a poor prognosis in glioma patients." (PMID 31599129, 2019). "Furthermore, it has been demonstrated that glioma cell-derived conditioned medium is able to increase STAT3 activity in microglia cells, leading to increased secretion of the anti-inflammatory M2-like cytokines IL-6 and IL-10." (PMID 29389898, 2018). "This decreased viability of glioma cells is also possible via SMAD4-induced negative regulation of NF-κB pathway in microglia, since recent studies have shown that SMAD4 knockdown in microglia induced pro-inflammatory cytokine, IL-6 in an NF-κB dependent manner." (PMID 29861845, 2018). "After migrating into the glioma environment, TAMs tend to possess the M2 phenotype, and their differentiation is driven by the secretion of immunosuppressive factors, including CSF-1, CCL2, IL-4, IL-6, IL-10, and transforming growth factor (TGF- β), from tumor cells." (PMID 30619286, 2018). "Although the cytokine assay performed in this study did not include all the angiogenic factors secreted by glioma cells, these results in our present study have indicated that M2-CM induced VM enhancement, at least partly via the IL-6 amplification in glioma cells." (PMID 27903982, 2017). "Therefore, this IL-6 and MMP14 axis between astrocytes and glioma cells may become a potential target for treatment of glioma patients." (PMID 27613828, 2016). "In fact, a causal link between IL6 and LC3B levels and hypoxia levels in gliomas has not been reported, and it is also unknown whether IL6 is involved in the upregulation of autophagy in such hypoxic areas." (PMID 27163161, 2016). "Differences were demonstrated between gliomas with and without IDH mutation, as transmigrated DCs exhibited delayed maturation due to the paracrine activity of 2-R-hydroxyglutarate in IDH-mutated gliomas, resulting in decreased expression of interleukin-6 and MHC-mediated antigen presentation." (PMID 38275375, 2023). "FTY720 could inhibit the growth, migration, and invasion of glioma by targeting GAMs to impede their effect on glioma cells, while also potentially blocking the chemoattraction of GAMs by inhibiting the MAPK-mediated secretion of IL-6 through the increased internalization of CXCR4." (PMID 34071306, 2021). "In addition, it could be speculated that, when PDIA3 is silenced and glioma cells are exposed to an activating stimulus, glioma cells are no longer able to release high amounts of IL6 and IL8 to induce the M2 phenotype in GAMs." (PMID 33153019, 2020). "Importantly, the aberrant expression of IL-6 in GBM cells is also interrupted by Ad-bFGF-siRNA, which could be a potential mechanism for Ad-bFGF-siRNA to serve as a targeted therapy for glioma in vitro and in vivo." (PMID 21906308, 2011). "Among these factors, IL-6 and EGF consistently promoted Pyk2 activation across all glioma cell lines tested, regardless of their baseline levels of total Pyk2 expression." (PMID 40867240, 2025). "Moreover, in glioma cells, insulin-like growth factor 1 (IGF-1) could induce TLR9 expression through hypoxia-induced factor 1 alpha signaling, which further leads to secretion of cytokines IL-1β, IL-6, IL-8, and CXCR4 (a chemokine receptor that plays an important role in cell migration)." (PMID 34715891, 2021).
glioma (continued). "In contrast, expression of IL-4, another important cytokine that regulates Mφ and T-cell functions similar to IL-6, did not correlate with CD40 expression in patients with GBM or all grades of glioma." (PMID 34103524, 2021). "In all glioma patients, we observed a positive correlation of percentage of CD14+ TREM-1+ cells with the IL-6/IL-10 ratio (P = 0.007) and a negative correlation with the plasma levels of IL-10 (P < 0.0001)." (PMID 32684831, 2020). "Furthermore, STAT3 target molecules such as IL-10 and IL-6 have been shown to activate STAT3, leading Li and Graeber to propose a feed-forward mechanism which may account for the constitutive activation of STAT3 in both glioma cells and glioma-infiltrating TAMs." (PMID 23737783, 2013). "In contrast to human U343 glioma cells, OSM treatment did not lead to an increased IL-6 expression in mouse and rat primary astrocytes (data not shown)." (PMID 21801384, 2011). "Interestingly, glioma tissue displayed an increase in pSTAT3 levels upon ITE+PD1 treatment, suggesting that IL-11 and IL-6 are likely not the primary regulators of STAT3 in this context and highlighting STAT3 as a potential target for combination therapy." (PMID 40283908, 2025). "Interestingly, IL-6, but not CSF-1, was preferentially localized in CD31+ ECs, implying that ECs as a major source for the expression of IL-6 but not CSF-1 in glioma microenvironment." (PMID 29422647, 2018). "When age was added to the model, neither plasma IL-6 or YKL-40 could differentiate GBM from gliomas of lower grade at a given age (IL-6, GBM vs. OII-III p = 0.81, IL-6, GBM vs. AII-III p = 0.88; YKL-40, GBM vs. OII-III p = 0.058; YKL-40, GBM vs. AII-III p = 0.29)." (PMID 32363159, 2020).
influenza (435 papers, 2008 to 2026). An acute viral infection of the respiratory tract, occurring in isolated cases, in epidemics, or in pandemics; it is caused by serologically different strains of viruses (influenzaviruses) designated A, B, and C, has a 3-day incubation period, and usually lasts for 3 to 10 days. "Another study similarly found that the relationship between serological response to influenza vaccination and pre-vaccine cytokines varied by strain, with IL-6 in that study being most strongly associated with immune responses against H3N2." (PMID 40881708, 2025). "IL‐6 is highly upregulated following influenza infection and has shown to be protective in animal models with IL‐6 deficient mice having increased mortality and lung damage compared to wild‐type controls." (PMID 39921246, 2025). "IL‐6 deficient mice infected with influenza have increased morbidity, mortality, and viral burden compared to wild‐type controls." (PMID 40420617, 2025). "Interleukin‐6 (IL‐6) is upregulated during both influenza and Covid‐19 infection and has been linked to disease severity." (PMID 40420617, 2025). "Cytokine, chemokine, and interferon levels are altered during influenza infection in IL‐6 deficient mice, including increased TGFβ by day 6 post‐infection and increased TNFα, IFNα, and CCL2 by day 7 post‐infection." (PMID 40420617, 2025). "Increased inflammatory monocytes, increased TNFα+ inflammatory monocytes, and decreased neutrophils have been observed in the airway compartment in IL‐6 deficient mice during influenza infection." (PMID 40420617, 2025). "The identified biomarker panel (CD4/CD8 ratio, IL-6, Kyn/Trp ratio) shows potential clinical promise for early risk stratification in high-risk pregnancies with influenza infection." (PMID 40558593, 2025). "IL-6 is involved in the development of cytokine release syndrome, with elevated levels of IL-6 and IL-1β being closely associated with poor prognoses in influenza patients and animal models." (PMID 40338080, 2025). "For the target search, we applied a PPI network to identify the top three hub genes associated with influenza (IL-6, HIF1A, and IL-1β)." (PMID 39000173, 2024). "Next, PPI network analysis identified the top three hub genes associated with influenza (IL-6, HIF1A, and IL-1β)." (PMID 39000173, 2024). "ROC curve analysis revealed showed that CRP ≥ 7.57 mg/L, Serum IL-6 ≥ 9.84 pg/ml, days from onset of Flu symptoms to hospitalization ≤4.5 days, CSF-TP ≥ 194.80 mg/L and FluA increased the risk of severe influenza combined with febrile seizures." (PMID 39507495, 2024). "Interleukin-6, a potent inflammatory cytokine, has been shown to limit the pathogenic inflammatory response in the lung during influenza infection in mice." (PMID 38400083, 2024). "IL-6 is an inflammatory marker, and clinical studies have shown that excess IL-6 in people with influenza is associated with adverse effects." (PMID 39203394, 2024). "We identified lutein as a main active compound in TE extract, and IL-6 as an important target associated with influenza, by using data mining and bioinformatics." (PMID 39000173, 2024). "Apart from analyzing antiviral activity, the authors also studied the levels of NF-κB and proinflammatory cytokines, such as TNF-α, IL-1β, and IL-6, generally associated with influenza infection, which were reduced by the treatment with the HA2 dendrimer." (PMID 38140131, 2023). "The lower expression of Aldh1a1 in the prenatal brain of mice exposed to MIA elicited by influenza, PolyI:C, and interleukin-6 has suggested that this gene is associated with aberrant neural development." (PMID 37851674, 2023). "A recent study has shown that the mice recovered from influenza infection are better protected from following Streptococcus pneumoniae infection, which is associated with a high IL-6–producing monocyte-derived AMs with enhanced bacterial killing capacity." (PMID 37615937, 2023).
influenza (continued). "When selenium is deficient in mice, the level of interleukin 6 (IL-6) increases substantially, but interferon-induced protein 10 (IP-10) is down-regulated during the influenza infection." (PMID 36837803, 2023). "For example, imprinted MO-AMs present after Influenza infection confer bacterial protection on an IL-6-dependent manner, whereas they increase susceptibility to a secondary Influenza infection in an IL-6-independent manner." (PMID 37081878, 2023). "Higher levels of interleukin 6 (IL‐6) are associated with the increased mortality of highly pathogenic influenza and SARS‐CoV‐2 infections; of note, IL‐6 signaling in humans is higher in winter than in summer." (PMID 35157360, 2022). "The increased serum levels of IL-6 and IL-10 immediately postoperatively were as high as documented in previous reports of influenza-associated encephalopathy in hypercytokinemia." (PMID 35219343, 2022). "For influenza+ at the acute timepoints, regions of relatively lower cytokine levels of IL-6, MIP-1α, IL-8, MIP-1β, MCP-1, were linked to higher levels of functional IFN-γ-producing immune cells, ASCs and activated cTfh1s." (PMID 33976217, 2021). "Despite their reported antiviral effect, IL-1β and IL-6 have been implicated in pulmonary inflammation during influenza infection." (PMID 34912341, 2021). "IL-6 has protective effects in experimental models of influenza, but in humans high levels of IL-6 are associated with severe infection." (PMID 32974217, 2020). "IL-6 has also been implicated in the cytokine storm initiated following influenza and severe acute respiratory syndrome (SARS) infections." (PMID 31675371, 2019). "IL-6 limits influenza-induced inflammation and lung pathology as IL-6-deficient mice exhibited higher fibroblast accumulation, a lower extracellular matrix (ECM) turnover, and higher mortality." (PMID 30333833, 2018). "IL-6 has been shown to modulate inflammation and affect adaptive immunity—IL-6-deficient mice are more susceptible to influenza infection —and to promote humoral responses by activating Th cells." (PMID 30241300, 2018). "Mortality related to infection with highly pathogenic influenza strains is associated with the production of high levels of inflammatory cytokines in the airways (in particular IL-6): the ‘cytokine storm’." (PMID 28195529, 2017). "We show that IL-6 is essential for the survival and the recovery from severe lung injury in mice after influenza infection, which is associated with reduced TGF-β production." (PMID 28262742, 2017). "Some of the same immune mediators, such as IL-6 that have been linked to inflammaging, frailty, and clinical outcomes, also play key roles in mediating and modulating immune responses to the influenza vaccine and infection." (PMID 26941738, 2016). "Some investigators have reported an association between high BALF IL-6 and increased influenza mortality." (PMID 25840995, 2015). "We have yet to determine the pathophysiological processes that underlie protection from ALI by TGF-β and/or IL-6 in influenza." (PMID 25840995, 2015). "IL-6 is rapidly released during the acute phase of influenza infection and its elevated levels are associated with disease severity triggered by H1N1 infection." (PMID 26067826, 2015). "Acute influenza infection with pulmonary complications was associated with high plasma concentrations of IL-1β, IL-6, IL-12, and IFN-γ." (PMID 24696530, 2014). "Smokers are at increased risk for influenza infection and we have previously shown that their nasal mucosal IL-6 and IP-10 responses to LAIV are blunted." (PMID 24910991, 2014). "Previous studies have shown that influenza infection causes an increase of immune cells in the blood, and that cytokines such as IL-6, IL-8 and MCP-1 protein levels differ significantly in macaques infected with different H1N1pdm strains." (PMID 22808249, 2012).